HIF1A (hypoxia inducible factor 1 subunit alpha)
Diseases named in the same sentence as HIF1A in open-access papers (continued):
Sharing a sentence is not in itself a finding about the gene and the disease.
cancer (continued). "However, extracellular citrate treatment in HCCs with high SLC13A5/NaCT expression had reduced glucose uptake due to HIF1α degradation, inducing the failure of metabolic adaptation to hypoxia, resulting in anti-cancer effects in in vitro and in vivo animal models." (PMID 35884416, 2022). "Therefore, studies on the synergistic mode of action of natural and synthetic compounds could pave a novel path in HIF-1α targeting anti-cancer therapy." (PMID 36014432, 2022). "Notably, BNIP3 is a well-known HIF-1α target gene and its expression, together with the consequent mitophagy activation and inhibition of c-Myc-dependent mitochondrial biogenesis, promotes cancer progression and resistance to chemotherapy." (PMID 35459212, 2022). "Furthermore, multitherapy that would include HIF-1α inhibition combined with chemotherapeutic regimens, radiotherapy, or other cancer gene-targeted reagents may be beneficial in clinical cancer therapy." (PMID 35607406, 2022). "Therefore, here, we describe the role of HIF-1α in regard to cancer progression." (PMID 35592530, 2022). "Hence, identification of these alternative mode of actions of different synthetic compounds targeting oncogenic pathways such as NF-κB and/PI3K-Akt could be a promising approach for HIF-1α targeted cancer therapy." (PMID 36014432, 2022). "Therefore, HIF-1α has been recognized as an important cancer drug target." (PMID 34969360, 2022). "Hence, the mTORC1/HIF1α/IGFBP5 axis may play a general role in restricting IGF1R-driven PI3K/AKT activity in (breast) cancer cells." (PMID 36093095, 2022). "Furthermore, it is possible that Treg recruitment by CXCR4 in these cancers could be modulated by treatment directed against hypoxia pathway factors, including HIF-1α." (PMID 35358193, 2022). "Additionally, oncogenes such as RAS, c-MYC, and HIF-1α are reported to induce glycolysis in cancer." (PMID 36313705, 2022). "Nevertheless, HIF-1α could also exert key regulatory functions on the cancer cells." (PMID 35295999, 2022). "Of note, hypoxia and HIF-1α pathway-induced phenotype alterations not only are limited in PD-L1 expression but also may influence other important characteristics and functions of cancer, such as EMT and glycolysis metabolism induction." (PMID 35295999, 2022). "Besides, HIF-1α induced expression of CD 47 on cancer cells to avoid phagocytosis by microphages." (PMID 35155430, 2022). "Adenosinergic effects appear dominant in untreated cancer within the TME because of the high levels of ectonucleotidases that catalyze the formation of this nucleoside, the induction of ADORA receptors, TGF-β, and associated HIF1α signaling responses driven by hypoxia." (PMID 35775486, 2022). "Moreover, mTOR is identified as an upstream activator of HIF-1α functions in cancer cells." (PMID 35163394, 2022). "Therefore, HIF-1α does have the ability to enhance phagocytosis of macrophages, which may be dependent on cancer types." (PMID 36071472, 2022). "Therefore, ROS accumulation in diabetic β-cells may induce Warburg-like lactate production by HIF-1α as observed in cancer cells, resulting in the disruption of glucose sensing and insulin secretion." (PMID 36139067, 2022). "Since STAT3 activation is sustained in efferocytic BM macrophages and considered a hallmark macrophage response to engulfing apoptotic cancer cells, it was hypothesized that STAT3 activation (phosphorylation at Tyr705) is critical in HIF-1α stabilization by efferocytosis." (PMID 36496973, 2022). "Thus, HIF-1α inhibition represents an interesting target for anti-cancer therapy." (PMID 35629169, 2022). "Thus, we investigated whether 6-gingerol treatment would downregulate cancer cell growth and target genes through the HIF-1α/HSP90 complex pathway under hypoxia." (PMID 35408505, 2022). "This may provide a new insight into the use of HIF1α to diagnose and treat human pan-cancer." (PMID 35860430, 2022).
cancer (continued). "Moreover, Hif1α was reported to elevate the expression of b-PIX which was identified as a fundamental driver of invadopodia formation so that augments the invasive potential in cancer cells." (PMID 35957827, 2022). "In addition, synergistic relationship between the phytochemicals and synthetic HIF-1α inhibitors could prove effective in managing different cancers." (PMID 36014432, 2022). "Therefore, inhibiting the expression of HIF-1α and blocking hypoxia signal transduction mediated by it may help develop novel therapeutic strategies for cancers." (PMID 36059955, 2022). "However, little is known about the specific role of HIF1α in pan-cancer." (PMID 35860430, 2022). "Additionally, it has been suggested that HIF-1α may have an impact on the metabolic alteration in cancer cachexia (CC)." (PMID 35205167, 2022). "Besides EMT, HIF1α induces the drug resistance in numerous cancer cells." (PMID 35355718, 2022). "Indeed, it has been demonstrated that hypoxia halts senescence in normal and cancer cell lines; thus, the downregulation of HIF-1α by topotecan may also contribute to the induction of senescence." (PMID 36362482, 2022). "Thus, HIF-1α inhibitors seem to be a promising cancer therapy in the future." (PMID 36212414, 2022). "As HIF-1α signaling could be regulated by ATP-associated signaling, we combined S3I-201 and LY294002 to co-target the upstream signaling components of the ATP-HIF-1α signaling pathway, and our in vivo mouse model showed increased drug sensitivity of cancer cells to chemotherapy." (PMID 35236823, 2022). "HIF1α simultaneously persuades the transcription of multiple genes, which can participate in the pathogenesis (angiogenesis, anaerobic glycolytic metabolism, pH regulation, cancer metastasis, erythropoiesis, and cell proliferation and survival) of cancer cells." (PMID 35847841, 2022). "HIF-1α, in response to the oxygen concentration in the lymph node microenvironment, could serve as an important transcriptionally regulatory mediator for a series of key phenotypes in the cancer cells, such as immune escape, EMT, and metabolism alteration." (PMID 35295999, 2022). "Therefore, targeting HIF-1α can be an effective way to control various crucial hallmarks of cancer." (PMID 36014432, 2022). "Importantly, in the HIF1A-knockout HepG2 cells, our qRT-PCR data confirmed the selected mRNA changes revealed by RNA-sequencing, and with TCGA pan-cancer data, we revealed that the expressional levels of these three genes, LUM, SCOC, and CCL2, were associated with immune cell infiltration levels." (PMID 35774500, 2022). "Therefore, DJ12 can be used as a significant HIF-1α inhibitor in various cancer types." (PMID 36014432, 2022). "Therefore, in view of the core role of HIF-1α in the metabolic reprogramming of cancer cells, which makes it an ideal target for cancer metabolic treatment, this study focuses on HIF-1α and attempts to intervene glycolysis of cancer cells by directly inhibiting its expression." (PMID 35350760, 2022). "Finally, cancer cell adaptations mediated by HIF1A, can also confer gemcitabine resistance." (PMID 36612058, 2022). "In addition to VHL mutations, alterations in two cancer suppressor proteins in the TCA, fumarate dehydrogenase (FH) and succinate dehydrogenase (SDH), may enhance HIF1-α stability and activity." (PMID 35745630, 2022). "HIF1α plays an important role in pan-cancer prognosis and immunotherapy, and it may be a novel biomarker with potential prognostic and immunotherapy roles in pan-cancer." (PMID 35860430, 2022). "Moreover, HIF-1α expression is related to poor OS in both genders; hence, it may be a potential therapeutic target for cancer stratification in both genders." (PMID 35845307, 2022). "Therefore, it was checked whether the HIF-1α expression of cancer cells would continue even when encapsulated in alginate." (PMID 36551144, 2022).
cancer (continued). "Therefore, we used mIF to analyze locally advanced NSCLC relapse-associated TME and explore its relationship with hypoxia-inducible factor-1α (HIF-1α), microvascular density (MVD), and cancer-associated fibroblasts (CAFs) in order to guide individualized therapy." (PMID 36685566, 2022). "Thus, hypoxia adaptation by HIF signaling (mainly overactivation of HIF-1α) promotes aggressiveness by several mechanisms in cancer cells but without establishing if there is a cause of chronic exposure." (PMID 34361103, 2021). "NO donors may be similarly useful in the treatment of other cancers by targeting the underlying HIF-1α-mediated chemotherapy resistance, although no active clinical trials that test the effectiveness of adding a NO donor alone to chemotherapy are underway." (PMID 33513777, 2021). "However, the prognostic value of HIF-1A in some cancers are still controversial, including GBC." (PMID 33403040, 2021). "For instance, HIF-1α may activate N-cadherin and vimentin to mediate EMT by promoting the loss of cell-cell adhesion which subsequently results in more migratory and invasive cancer cells." (PMID 33546106, 2021). "Interestingly, we performed tissue IF to detect HIF-1α expression in the cancer tissues." (PMID 33819917, 2021). "Considering its crucial role in cancer progression, HIF1α as a transcription factor is involved in several signaling pathways and overlapping molecular mechanisms, each of which could be an encouraging target to be investigated in cancer studies." (PMID 33602983, 2021). "We believe that pharmacological inhibitors of HIF-1α and modulators of ER stress, although characterized by low specificty and anti-cancer efficacy when used as single agents, may be repurposed as chemosensitizers against hypoxic and chemorefractory tumors in the next future." (PMID 33423689, 2021). "In normoxia, HIF1α and SOX2 are inversely correlated, reprogramming cancer cells towards an OxPhos profile, while under hypoxic conditions, as well as in acidosis-exposed cells, the increased lactate production may promote HIF1α stabilization reducing PGC1α towards a glycolytic re-conversion." (PMID 34768751, 2021). "In addition to cancer progression, HIF1-α plays an important role in inflammatory diseases." (PMID 34571724, 2021). "Previous work on cancer cells derived from patients with a broad spectrum of solid tumours has shown that hypoxia leads to the induction of complex signalling networks such as the hypoxia‐inducible factor 1α (HIF‐1α) and its downstream targets and transcriptional regulators, including CAs." (PMID 34791807, 2021). "Thus, SPRY4-IT1 comprises an additional layer of HIF-1α regulation in cancer cells." (PMID 34163032, 2021). "Therefore, concurrent targeting MYC and HIF1α may represent a better, more effective way for cancer with high expression of MYC and/or HIF1α." (PMID 33572152, 2021). "ROS may modulate cancer cell metabolism by acting as secondary messengers in the signaling pathways involved in cellular proliferation and metastasis, such as those mediated by nuclear factor kB (NF-kB) and hypoxia inducible factor 1 α (HIF-1α)." (PMID 34205678, 2021). "Therefore, adequate study design and pre-clinical models are needed to determine whether the HIF-1α initiates cancer." (PMID 34154667, 2021). "Therefore, we assume that NMs may contribute to cancer development by inducing ROS-mediated inflammation via activating NF-κB signaling and hypoxia via activating HIF-1α signaling." (PMID 33863340, 2021). "However, there are few reports indicating that HIF-1α overexpression may be connected to a positive outcome in certain cancer types including head and neck, non-small cell lung and neuroblastoma." (PMID 33499237, 2021). "Therefore, inhibitors of HIF-1α are highly likely to improve cancer prognoses by inhibiting EMT." (PMID 34829545, 2021).
cancer (continued). "As the same involvement of HIF-1α in cancer cell protection from apoptosis took place in the case of genotoxic treatments with etoposide or doxorubicin, the analogous GRP75-dependent antiapoptotic mechanism may protect hypoxia-adapted cells from apoptosis following radiation exposure." (PMID 33806538, 2021). "However, HIF-1α may temporally maintain cancer cells in a quiescent state and conserve their survival as long as oxygen supply is available, where they become more invasive." (PMID 33472628, 2021). "PKM2 enzyme acts as a coactivator of HIF-1α itself to stimulate chromatin binding, coactivator recruitment, and transcriptional activation, leading to a metabolic reprogramming of cancer cells and favoring other processes of cancer progression, such as angiogenesis." (PMID 34071836, 2021). "Similarly, targeting CDK4/6 using FDA-approved inhibitors in combination with HSP90 inhibition shows a class effect on HIF1α inhibition and cancer cell viability suppression not only in colorectal but also in various other cancer types, including Rb-deficient cancer cells." (PMID 34686682, 2021). "We investigated the hypothesis that CDK1 and HSP90 signaling overlaps in the regulation of HIF1α, and combination treatment to target both CDK1 and HSP90 may lead to enhanced inhibitory effects towards HIF1α expression and function as well as improved anti-cancer efficacy." (PMID 34686682, 2021). "Mitophagy allows cancer cells to recover ATP, redox metabolites and building blocks, that can be used to re-synthesize biomolecules damaged by chemotherapeutic drugs, providing an additional mechanism by which the altered mitochondrial metabolism induced by HIF-1α determines chemoresistance." (PMID 33423689, 2021). "However, autophagy may itself also regulate HIF-1α stability, and this might partially explain the opposing roles of autophagy in malignant tumors." (PMID 33573362, 2021). "As both HIF-1α and DPT have been reported to beassociated with cancer cell cycle progression, cancer cell microtubule destabilization, cancer cell necroptosis and autophagy, our data suggest that the effect of DPT on cancer cells might occur through the degradation of HIF-1α." (PMID 33732648, 2021). "Furthermore, hypoxia increases hypoxia-inducible 1alpha (HIF1α) in cancer cells." (PMID 34371753, 2021). "Thus, based on these studies, it is evident that agents blocking HIF-1α expression or inhibiting HIF-1α activity may be useful in improving current cancer therapies." (PMID 34681797, 2021). "Arsenic trioxide could promote the apoptosis of cancer cells via hypoxia-inducible factor (HIF)-1α." (PMID 34880920, 2021). "Although the mechanism through which these small-molecule inhibitors affect cancer immunotherapy remains unclear, the loss of HIF-1α adversely affects CD8+ T-cell infiltration, resulting in the loss of antitumor activity in cancer immunotherapy models and finally leading to accelerated tumor growth." (PMID 34943817, 2021). "Thus, the role of HIF-1α in growth, altered energy metabolism, invasion, and metastasis of cancer cells is important, and it may be an effective target for cancer treatment." (PMID 32847004, 2020). "Furthermore, these cancer-cell derived exosomes could induce angiogenesis via HIF-1α signaling in vitro when internalized by HUVECs." (PMID 33469537, 2020). "We, in turn, observed IL13Ra1 in tumors to correlate positively with expression of genes encoding proteins involved in promoting cancer, especially those facilitating invasion and metastasis such as α smooth muscle actin, HIF1α, and VEGF-A, although not with proliferation marker Ki67." (PMID 32512917, 2020).
cancer (continued). "From a therapeutic standpoint, the current report also opens the door to explore whether targeting Nrf2 can improve therapeutic outcome for cancer patients by specifically blocking the Nrf2 activity on HIF1α, glycolysis and the stemness genes to eliminate CSCs." (PMID 32226544, 2020). "However, it remains elusive whether HIF-1α-target miRNAs could affect the chemo-sensitivity of cancer cells." (PMID 32522234, 2020). "Interestingly, Spivak-Kroizman and collaborators revealed that elevated secretion of SHH ligand by cancer cells (mediated via HIF-1α) could be responsible for the prevalence of desmoplasia in this type of cancer." (PMID 32707920, 2020). "Hence, if ROS levels are below the cytotoxic threshold to induce cell death, they become advantageous molecules for cancer cells, by increasing the amount of HIF-1α and stimulating the metabolic adaptation to hypoxia, as well as the pro-survival and pro-invasive programs induced by hypoxia." (PMID 33291643, 2020). "Therefore, we hypothesize that the hypoxia/Hif1α-dependent regulation of the metabolism in cancer is modulated through Fbp2, and is based on the energy and redox state of a cell." (PMID 31947613, 2020). "However, in cancer cells, HIF-1α interaction with hypoxia response element (HRE) in the programmed cell death ligand 1 (PD-L1) promoter can trigger rapid expression of this immune checkpoint molecule, which is also capable of signaling more effectively in the lactate-rich TME." (PMID 35047983, 2020). "In addition, the expression of various miRNAs, including miR-33a, miR-494, miR-145, miR-191, miR-27a, miR-424, miR-205, miR-21, miR-185, miR-101, miR-210-3p, miR-224-3p, miR-15a, miR-21, and miR-107, has been proven to be HIF-1α-dependent in the progression of various cancers." (PMID 32014012, 2020). "Consequently, frequent downregulation of HITT in cancer results in increased HIF-1α expression." (PMID 32640630, 2020). "Cancer cell-derived ROS could down-regulate the expression of caveolin 1 (CAV1) in CAFs, and the loss of CAV1 also leads to increased ROS levels, thereby stabilizing HIF-1α." (PMID 32787888, 2020). "Furthermore, some results suggest that downregulation of HIF1a may decrease the proliferation and invasive ability of various types of cancer cells." (PMID 32872192, 2020). "In addition, andrographolide reduced hepatoma cancer cells’ growth, inhibiting vascular endothelial growth factor A expression via HIF-1α degradation, which also suggests that andrographolide could interfere with cell metabolism in cancer." (PMID 33374961, 2020). "In addition, the levels of HIF-1α accumulation were much higher in cancer samples." (PMID 33295886, 2020). "Cancer causes inflammation, which results in the activation of transcription factors that further increase the inflammatory response, such as nuclear factor-kB (NF-kB), signal transducer and activator of transcription 3 (STAT3), and hypoxia-inducible factor 1a (HIF1a)." (PMID 32716955, 2020). "In addition, it has been shown that HIF-1α can induce EMT in many types of cancer tissues." (PMID 32596377, 2020). "Therefore, identification of crosstalk between HIF-1α and Drp1 could provide novel insights for developing cancer therapies." (PMID 33178201, 2020). "In this respect, the growth of cancer cells under chronic stress appears to be regulated by the HIF-1/BAR2 axis as demonstrated by the finding that resveratrol inhibits the proliferation of chronically stressed cancer cells by preventing the upregulation of both HIF-1α and BAR2." (PMID 32917020, 2020). "Moreover, HIF-1α was accumulated in the nuclei of cancer cells in vivo." (PMID 33330441, 2020). "Since Fbp2 oligomerization state and thus, its role is regulated by AMP and NAD+—crucial indicators of cellular metabolic conditions—we hypothesize that the Hif1α-dependent regulation of the metabolism in cancer is modulated through Fbp2, a sensor of the energy and redox state of a cell." (PMID 31947613, 2020).